INS (insulin)
Diseases named in the same sentence as INS in open-access papers (continued):
Sharing a sentence is not in itself a finding about the gene and the disease.
diabetes (continued). "However, we matched CKD, diabetic retinopathy, and DCSI scores to balance the diabetes complications; we also matched the number of oral antidiabetic drugs, use of insulin, and duration of diabetes to balance the severity of T2D between the matched case and control groups." (PMID 38117497, 2023). "In addition, IR could also be triggered by high glucose concentration or combined treatment of high glucose and insulin in vivo in other reports, suggesting that IR may be an inevitable phenotype of diabetes." (PMID 37386367, 2023). "The World Health Organisation defines diabetes mellitus as a metabolic disorder of multiple aetiology characterised by chronic hyperglycaemia with disturbances of carbohydrate, lipid, and protein metabolism resulting from defects in insulin secretion, insulin action, or both." (PMID 36674502, 2023). "Women who had diabetes during pregnancy had a significantly reduced waist circumference and subcutaneous fat thickness after one year (p < 0.001 and p = 0.05, respectively), as well as significantly higher levels of insulin and ghrelin (p < 0.001) and lower levels of resistin (p = 0.005)." (PMID 38004222, 2023). "Our results suggest that YM enhances glucose tolerance because of its positive effects on GSIS, oxidative stress rate and insulin sensitivity in rat islets, suggesting that long-term dietary supplementation with YM may improve glucose homeostasis in pre-diabetes or type 2 diabetes." (PMID 37514235, 2023). "The review also focuses on the receptors like GPCR 119, GPER, Vaspin, Metrnl, Fetuin-A that have role in insulin regulation and have potential to become future targets in treatment for diabetes that may be effective and safer as compared to the conventional and current treatment approaches." (PMID 36782201, 2023). "Furthermore, we found that impairment of Gls2 expression in pancreatic β-cells during hyperglycaemia resulted in the development of significant diabetes mellitus via impairment of insulin increase along with a paradoxical increase in glucagon despite the high plasma glucose." (PMID 37147373, 2023). "Furthermore, the illustrative case presented exhibits the other major benefits of advanced diabetes technologies such as AHCL insulin delivery systems through their capacity to alter insulin delivery in times of rapid change of glucose levels, as well as alarm the user or others to potential harm." (PMID 37864225, 2023). "Since diabetes is caused by decreased insulin action in various tissues, impaired insulin action in the liver or other tissues may lead to carcinogenesis supported by driver mutations in STAM mice and in patients with diabetes and NASH." (PMID 37852976, 2023). "However, the DEGs obtained in each dataset were enriched in pathways related to diabetes, such as alteration in glycolysis, pyruvate metabolism, cholesterol metabolism, Insulin/IGF pathway, pancreatic secretion, and MAPK signaling, all of which are well-known to be associated with T2D9,10." (PMID 37221264, 2023). "Thus, alterations in proteins involved in diabetes-induced insulin resistance, as part of the insulin signaling cascade, may compromise healthy follicular development in the ovaries and interfere with the reproductive process." (PMID 37892483, 2023). "These people could benefit from taking some natural substances that have been researched to verify their positive action in reducing IR and insulin levels, with the aim of slowing down evolution toward overt diabetes, but above all, to prevent cardiovascular damage." (PMID 37298967, 2023). "Diabetes mellitus (DM) is a metabolic disorder characterized by elevated levels of blood glucose (BG) due to compromised insulin secretion, impaired insulin action, or a combination of both." (PMID 38111457, 2023). "Diabetes mellitus (DM) is a group of metabolic disorders characterized by chronic hyperglycemia that have multiple etiologies, all of which manifest as defects in insulin secretion and/or utilization." (PMID 38169604, 2023).
diabetes (continued). "However, the global amino acid metabolism across the kidney was not altered in either insulin-deficient diabetes or insulin deprivation." (PMID 38201949, 2023). "Numerous studies have demonstrated that the consumption of various biologically active compounds, adjacent to insulin treatment, have the ability to effectively regulate postprandial glycemia and can be used as alternatives to drugs for the development and control of diabetes." (PMID 37627632, 2023). "Notably, in recent years, nucleic acids containing exosomes-especially miRNAs and lncRNAs-have been revealed to modulate communications between organs in pathological processes of diabetes, including affecting metabolic signals and insulin signals in target tissues and cell viability." (PMID 37740187, 2023). "Therefore, the pharmacological blockade of GIP_HUMAN signaling may be a promising tool for improving insulin production and may attenuate cardiovascular complications in diabetes and metabolic syndrome." (PMID 37895259, 2023). "In addition to insulin levels, there is a type of diabetes related to the respiratory chain, called mitochondrial diabetes, caused by the dysfunction of insulin secretion due to an inhibition of the production of adenosine triphosphate (ATP), which is needed for insulin secretion." (PMID 37370930, 2023). "Similarly, patients with diabetes have a higher prevalence of psoriasis, which may be associated with insulin use, and DPP-4 inhibitor, a drug used for diabetes, has been shown to ameliorate psoriasis." (PMID 36837593, 2023). "Diabetes mellitus (DM), a complex heterogeneous metabolic disorder characterized by a defect in the function of insulin, is on the rapid rise globally." (PMID 38033739, 2023). "Notably, the same mis-splicing events are also observed in the pathogenesis of T2D and may explain much of the disruption in first-phase insulin secretion observed in pre-diabetes and diabetes." (PMID 38007492, 2023). "Diabetes mellitus (DM) is a chronic metabolic disorder categorized by elevated levels of plasma glucose due to defects in insulin secretion (type I), insulin action (type II), or both." (PMID 37384652, 2023). "Diabetes mellitus (DM) is the most common metabolic disorder characterized by hyperglycemia resulting from inappropriate insulin secretion or resistance." (PMID 38060705, 2023). "According to this idea, a diet with a lower GI may result in slower rates of digestion and absorption, which may decrease the rapid rise in postprandial hyperglycemia and insulin concentration, as well as subsequently have an impact on the treatment of diabetes." (PMID 37835312, 2023). "Furthermore, hypercholesterolemia may occur when a person has diabetes because insulin inhibits β-hydroxy-β-methylglutaryl coenzyme-A (HMG-CoA) reductase, a major rate-limiting enzyme called in the degradation of cholesterol-rich LDL components." (PMID 36983154, 2023). "Diabetes mellitus (DM) is a chronic disease characterized by elevated blood glucose levels due to the body’s inability to produce sufficient insulin or use it efficiently." (PMID 37873836, 2023). "Additionally, a post-hoc analysis of the LixiRam randomized trial's data was done to evaluate the safety of a treatment plan using lixisenatide and basal insulin in people with type 2 diabetes mellitus (T2DM) while fasting during Ramadan was examined in the study." (PMID 38169925, 2023). "Diabetes mellitus (DM) is a group of metabolic disorders distinguished by chronic high blood glucose levels (hyperglycemia) resulting from the impairment of insulin action, insulin secretion, or both." (PMID 38022364, 2023). "Diabetes mellitus (DM) is a chronic heterogeneous metabolic disorder represented by the incidence of hyperglycemia due to a defect in function or secretion of insulin." (PMID 38033739, 2023).
diabetes (continued). "Prior to advanced diabetes technology such as CGMs and the automated insulin delivery systems, several of these earlier studies demonstrated that the scrupulous avoidance of recurrent episodes of hypoglycemia could restore (at least partially) awareness of hypoglycemia." (PMID 37942482, 2023). "Diabetes mellitus (DM) is a metabolic disorder characterized by either insulin resistance or the inability of the body to produce a proper amount of insulin or both, resulting in hyperglycemia." (PMID 36974251, 2023). "Individuals living with diabetes are at increased risk of developing anxiety because of concerns about dietary restrictions, taking several medication and insulin injections, constant checking of blood glucose, and lack of support from family and medical practitioners." (PMID 37836510, 2023). "Therefore, drugs that target insulin signaling pathways or glucose metabolism may have potential in treating both diabetes and breast cancer." (PMID 37165049, 2023). "Pioglitazone (PIO), a diabetes drug, improves the effect of insulin/leptin in the hypothalamus, partly by activating the Adipo/AdipoR1/AMPK axis in the hypothalamus, suggesting that Adipo and AdipoR1 may play an important role in improving the effect of IR in hypothalamus." (PMID 37034166, 2023). "Similarly, with SHAP, DT and KNN resulted in the highest AUC value of 0.77 with associated risk factors, such as systolic blood pressure, history of hypertension, diabetes mellitus duration, insulin treatment, fasting plasma glucose, and glycosylated hemoglobin." (PMID 37370980, 2023). "Diabetes mellitus (DM) is a chronic metabolic disease characterised by hyperglycemia, which occurs due to impaired insulin secretion, insulin action, or both." (PMID 38813039, 2023). "Dogs and cats with diabetes mellitus (DM) are frequently treated with exogenous insulin and a specific diet and require regular monitoring to ensure appropriate dosing." (PMID 36977242, 2023). "In patients with diabetes aged 30–70 years, consuming two meals per day, that is, breakfast and lunch, was found to be a more effective strategy for managing fasting plasma glucose, C-peptide, glucagon, and insulin sensitivity levels than consuming six meals per day." (PMID 37165359, 2023). "Poor glycaemic control in this individual indicates the problem of clinical inertia because earlier initiation of insulin should have occurred as part of optimal diabetes therapy, which may have been more successful if the correct diagnosis of LADA had been made." (PMID 37234800, 2023). "These metabolite concentrations, which are strongly connected to intestinal barrier function, blood glucose and lipid levels, insulin sensitivity, and inflammatory levels, may account for the role of Astragali Radix in a range of metabolic diseases, including diabetes." (PMID 37638043, 2023). "By harnessing the potential of these small vesicles, it may be feasible to develop targeted interventions that enhance insulin secretion and improve glycemic control, offering hope for more effective diabetes management and the mitigation of related complications." (PMID 38027137, 2023). "Also, insulin may be difficult to obtain after hurricanes, and difficult to store adequately during power outages, which could lead to poor control of diabetes." (PMID 37254127, 2023). "Diabetes mellitus (DM) is a chronic and lifelong illness with growing incidence globally and is characterized by inadequate insulin secretion." (PMID 37337224, 2023). "Diabetes mellitus (DM) is a metabolic disorder characterized by impaired insulin secretion and/or insulin action resulting in hyperglycemia." (PMID 37763329, 2023). "An autoimmune reaction against the proteins produced by β-islet cells of the pancreas is a major cause of type 1 diabetes mellitus (T1DM), while type 2 diabetes mellitus (T2DM) may arise from insulin resistance, impaired insulin secretion, and lifestyle habits." (PMID 37759824, 2023).
diabetes (continued). "Together, oxidative stress and inflammation have been implicated in mediating the damage to myelinated tracts, synaptic contacts, and hippocampal neuronal circuits, which may explain the cognitive impairments observed in animal models of diabetes and impaired insulin signaling]." (PMID 37443762, 2023). "The upregulation of Ptpn1 in tissues and cells inactivates protein tyrosine kinase (PTK), blocks the effect of insulin on binding to insulin receptors and dephosphorylation of tyrosine residues on insulin receptors substrates, leading to insulin resistance and finally to diabetes." (PMID 37033250, 2023). "Using the random forest model, Qian Li proved that changes in the gut microbiota could be used to identify individuals with a high risk of Type 2 diabetes, since the intestinal mucosal barrier is essential for improving insulin sensitivity and preventing the development of diabetes." (PMID 37337143, 2023). "Diabetes mellitus (DM) is identified by chronic hyperglycemia and impaired carbohydrates, protein, and lipid metabolism due to complete or partial disability of insulin secretion/action." (PMID 36839357, 2023). "Thus, some manifestations of diabetes mellitus are related to glucose depletion inside insulin-dependent cells, others are related to glucose excess toxicity in relation to other cells and tissues, and more—to oxidative stress or using alternative substances as energy sources." (PMID 37373216, 2023). "This is a case of a 34-year-old male, Filipino, diagnosed with type 2 diabetes mellitus, who was maintained on dapagliflozin + metformin 5mg/1000mg taken twice a day with good compliance and was admitted with EuDKA precipitated by decreased food intake and managed with intravenous insulin." (PMID 38143642, 2023). "Thus, the patients who developed OCADs in our study would have extensive CADs, which is expected in those with advanced diabetes requiring insulin therapy, and the use of a DPP‐4i could be particularly beneficial in these patients." (PMID 37528628, 2023). "Besides self-reported data on parental involvement in diabetes management, using logbooks for activities such as insulin injection and blood glucose monitoring may provide a more objective methodology for understanding the distribution of responsibility." (PMID 40303254, 2023). "Diabetes is a chronic, multifactorial, polygenic, potentially reversible disease characterized by chronic hyperglycemia in relation to decreased insulin production, decreased insulin sensitivity by the target tissues (i.e., adipocyte, muscle, or liver), or a combination of both." (PMID 37675359, 2023). "In the Diabetes Prevention Program, it has been shown that a 7% body weight loss with 54% carbohydrate‐containing MNT and accompanying physical activity reduces the progression of T2DM by 58% and results in an improvement in insulin resistance‐related parameters." (PMID 38107130, 2023). "Diabetes mellitus (DM) is a serious public health issue marked by metabolic derangements and dysregulated glucose homeostasis due to insufficient insulin secretion and/or insulin resistance." (PMID 37719634, 2023). "The glucokinase regulatory protein (GCKR) regulates glycogen metabolism and insulin secretion, and the GCKR rs1260326 is a putative single nucleotide polymorphism (SNP) associated with metabolic disorders including nonalcoholic fatty liver disease (NAFLD) and type 2 diabetes mellitus (T2DM)." (PMID 37829557, 2023). "Diabetes mellitus (DM) is a metabolic disease characterized by chronic hyperglycemia associated with impaired carbohydrate, lipid, and protein metabolism, with concomitant absence of insulin secretion or reduced sensitivity to its metabolic effects." (PMID 37998439, 2023). "Similarly, dietary fiber could increase the flora gene richness and activate acetic acid and butyric acid synthesis pathways to promote insulin secretion and intervene in diabetes by modulating gut microbiota." (PMID 36986086, 2023).
diabetes (continued). "Participants with diabetes had significantly higher C-reactive protein (CRP) concentrations, with the median value being in the high clinical risk category, i.e., >3 mg/L, as well as a higher percentage of HbA1c, and fasting blood glucose and fasting insulin concentrations (p < 0.0001)." (PMID 37891943, 2023). "Diabetes mellitus (DM), a persistent metabolic disorder, is characterized by insufficient insulin secretion from the pancreas and/or resistance to insulin in peripheral tissues." (PMID 37462847, 2023). "Moreover, a cross-sectional retrospective study in Poland among older patients admitted to geriatric wards reported an overall lower percentage of patients prescribed insulin (32.9%) but higher percentages (56.9%) were found among patients with uncontrolled diabetes." (PMID 36767972, 2023). "The intestinal microbiota can affect body weight, insulin sensitivity, sugar, and lipid metabolism, which is why it has been hypothesized that its changes may contribute to the pathogenesis of obesity and diabetes." (PMID 37763199, 2023). "A metabolic condition known as diabetes mellitus (DM) is characterized by decreased insulin secretion and dysfunction of pancreatic cells." (PMID 37823087, 2023). "Therefore, this study identifies a novel signaling machinery regulating glucose-stimulated insulin secretion, which might be a potential target for the therapy of diabetic mellitus." (PMID 36822326, 2023). "Moreover, we speculate that utilization of the daily nutrition program and the insulin equation may have eased the burden of diabetes-related decision making, further promoting the athlete’s well-being during the case study." (PMID 37999431, 2023). "Since the insulin signaling pathway is a significant mediator for both AD and diabetes, studies have postulated insulin resistance as a major connection for the regulation of crosstalk between the periphery and brain and as a preliminary step for the relationship between diabetes and AD." (PMID 37508448, 2023). "Diabetes mellitus (DM) is a chronic metabolic disorder characterized by glucose tolerance, hyperglycemia and insulin resistance, with features such as high fasting and post-prandial blood glucose concentration resulting from defective insulin secretion, insulin action, or both." (PMID 37200359, 2023). "Therefore, FABP4 might influence insulin resistance and insulin secretion in diabetes mellitus type 2." (PMID 37892985, 2023). "IgG subclass responses to insulin may vary with diabetes type." (PMID 37143729, 2023). "In addition, diabetes duration (OR 1.17, 95% CI 1.14-1.21, P < 0.001), HbA1c (OR 1.62, 95% CI 1.41-1.85, P < 0.001), insulin (OR 4.43, 95% CI 3.82-5.71, P < 0.001), and oral antidiabetic drugs (OR 3.11, 95% CI 2.00-4.83, P < 0.001) were associated with diagnosis of DR compared to the no DR group." (PMID 37206443, 2023). "Diabetes mellitus (DM) is a chronic metabolic disorder characterized by impaired insulin secretion or insulin resistance, which affects approximately 10.5% of the global adult population aged between 20–79 years." (PMID 37903776, 2023). "However, in this study, although we took insulin resistance into account in this work, due to many of our diabetes patients receiving insulin therapy, we evaluated insulin resistance based on FCP levels and FPG levels, rather than fasting insulin levels and FPG levels." (PMID 37443036, 2023). "Diabetes mellitus (DM) refers to a group of metabolic disorders characterized by chronic hyperglycaemia resulting from defects in insulin secretion, insulin action, or both." (PMID 37372112, 2023). "In conclusion, this population-based cohort study indicates that survival in esophageal cancer was negatively associated with diabetes but positively associated with metformin use and not with other antidiabetic medications (ie, sulfonylureas, insulin, or thiazolidinedione)." (PMID 37314979, 2023).